SIRT6 (sirtuin 6)
Diseases named in the same sentence as SIRT6 in open-access papers (continued):
Sharing a sentence is not in itself a finding about the gene and the disease.
tumor (continued). "Notwithstandingthe great number of reports indicating the tumor-suppressorrole of SIRT6 in many forms of cancer, some evidence points towardan oncogenic role of SIRT6 under specific conditions." (PMID 34213345, 2021). "As seen for plasma levels, Cxcl10 mRNA expression was also significantly reduced in gastrocnemius muscle of Tu‐Sk.T6Tg mice, compared with that in Tu‐CN mice, indicating a direct transcriptional regulation of Cxcl10 by SIRT6 in the context of tumour." (PMID 34212132, 2021). "Here, we show that a heterozygous deletion of the Sirt6 gene increases tumor latency and improves overall survival in the MMTV-PyMT mouse model." (PMID 33482921, 2021). "In experiments on mouse models and human cell cultures, Hui-Ju Ch’ang at the National Institute of Cancer Research in Zhunan, Taiwan, and co-workers found that KLF10 binds to and upregulates another tumor suppressor gene, SIRT6." (PMID 34702956, 2021). "By reducing Cxcl10 mRNA expression in muscle as well as due to downregulation of circulating CXCL10 level, SIRT6 probably helps to avoid β‐cell destruction, maintaining insulin level and thereby inhibiting tumour progression." (PMID 34212132, 2021). "Functional knockdown of SIRT6 results in tumor cell proliferation, invasive profile, and antiapoptotic effect." (PMID 33440786, 2021). "On the other hand, SIRT6 has contrasting rolesin cancer, acting either as a tumor suppressor or promoter in a context-specificmanner." (PMID 34213345, 2021). "Sirt6 is involved in multiple biological processes, including aging, metabolism, and tumor suppression." (PMID 33727672, 2021). "Silencing SIRT6 by siRNA delivered through engineered exosomes inhibited tumor growth and metastasis." (PMID 33995674, 2021). "Combined with the results of previous experiments, our results demonstrate that α-hederin activates SIRT6 expression and regulates tumour glycolysis." (PMID 33356727, 2021). "It has been exhibited that SIRT6 promotes tumor suppression inhibiting the hypoxia-inducible factor-1α (HIF-1α), which prevents the glycolytic metabolism of cancer cells." (PMID 33920726, 2021). "To further determine the antitumor activity of aptamer-modified exosomes loaded with SIRT6 siRNA, we utilized the subcutaneous tumor model." (PMID 33995674, 2021). "Together, our observations demonstrate a novel tumor suppressive mechanism of SIRT6 on cancer cell adhesion and migration through the control of ACLY-dependent gene regulation." (PMID 34573442, 2021). "Taken together, these results indicated that in our mouse model of cancer‐cachexia, skeletal‐muscle specific over‐expression of SIRT6 increased plasma insulin levels, which likely contributed to reduce tumour growth and to preserve muscle mass." (PMID 34212132, 2021). "Tumor masses developed from SIRT6-silenced MDA-MB-231 cells exhibited a markedly reduced growth, which was also confirmed by isolating the tumor masses at the end of the experiment and by measuring their size and weight." (PMID 33482921, 2021). "The in vitro experiments conducted in PC3M-luc also confirmed the tumor-promoting function of SIRT6." (PMID 33995674, 2021). "SIRT6 in tumorigenesis can be considered a double-edged sword, acting either as tumor promoter or suppressor depending on the biological context, and several reports underlined the connection between its action and the modulation of cell death in cancer." (PMID 33800266, 2021). "In tumour‐bearing mice, SIRT6 over‐expression preserved muscle weight (P < 0.001) and fibre size (P < 0.005) as well as suppressed tumour growth (P < 0.05)." (PMID 34212132, 2021). "Among tumor specific enzyme isoforms, SIRT6 deacetylates PKM2 at K433, leading to its nuclear export and the inhibition of PKM2 oncogenic functions." (PMID 32117717, 2020). "This suggests that SIRT6 acts as a tumor suppressor in the development of tumors by inhibiting glucose metabolism." (PMID 33109235, 2020).
tumor (continued). "High SIRT6 expression was also related to a favorable tumor node metastasis (TNM) stage (OR = 0.44, 95% CI = 0.28–0.70) among gastrointestinal cancer patients." (PMID 33335996, 2020). "LINC00319 was shown to promote the proliferative, migratory and invasive capabilities of tumor cells by stabilizing SIRT6 or by interacting with miR-1207, miR-450 and miR-32." (PMID 32194636, 2020). "The administration of SIRT6 inhibitors should be done with caution, limiting it to defined time windows, taking into account that this enzyme also has a role as a tumor suppressor in certain tissues and that complete SIRT6 depletion can be very detrimental." (PMID 32736564, 2020). "Overall, SIRT6 can act as a tumor suppressor, and an increase in SIRT6 activity or protein levels contributes to a tumor suppression, indicating a promising strategy for cancer prevention." (PMID 32905943, 2020). "The incidence of nearly all types of cancers increases with age in humans, and SIRT6 has been characterized as a tumor suppressor in several organs." (PMID 32789493, 2020). "In the present study, CQ promoted tumor growth by increasing the Warburg effect in SIRT6-overexpressing PTC cells." (PMID 32983963, 2020). "Sirt6 has been identified as a tumor suppressor and hence Sirt6 activators are the focus of drug discovery efforts regarding this phenotype." (PMID 32426286, 2020). "The results showed that high SIRT6 expression was related to a favorable tumor node metastasis (TNM) stage (OR = 0.44, 95% CI = 0.28–0.70, P = 0.001; I2 = 23.7%, P = 0.263, fixed-effects model)." (PMID 33335996, 2020). "Sirt6 is a double-edged sword in carcinogenesis, as it possesses both oncogenic and tumor suppressive abilities due to the complexity of its upstream and downstream signaling pathways." (PMID 32711549, 2020). "SIRT6 was shown to be both a tumor suppressor and a promoter depending on the tumor type and cellular context, which adds more complexity in predicting the net biologic effects of its activation by DAC35." (PMID 32587297, 2020). "SIRT6 plays essential roles in metabolism, tumor suppression, and DNA repair through the deacetylation of histone substrates." (PMID 33067423, 2020). "Especially, the effect of SIRT6 in tumor growth has been reported controversially according to the type of cancer." (PMID 33198792, 2020). "Sirt6 suppresses tumor growth mainly through suppression of anaerobic glycolysis and co-suppression of MYC, thereby inhibiting cancer occurrence and development." (PMID 32711549, 2020). "In vivo investigations revealed that OSS_128167 administration or shSirt6 transfection mediated Sirt6 downregulation, both resulted in inhibition of tumor growth in xenograft models of DLBCL." (PMID 32711549, 2020). "Our previous study had confirmed that SIRT6 increases tumor invasion by inducing the epithelial-mesenchymal transition." (PMID 32983963, 2020). "In summary, our study demonstrates that SIRT6 is a critical tumor suppressor in melanomagenesis that functions by promoting the repair of UV-induced DNA damage through GG-NER." (PMID 32789493, 2020). "Compared to the group receiving only doxorubicin treatment, tumor growth was significantly decreased with knock-down of SIRT6." (PMID 33198792, 2020). "SIRT6 overexpression significantly inhibited the Warburg effect and tumor growth; however, CQ rescued the inhibition." (PMID 32983963, 2020). "Once a tumor forms, tumor cells can take advantage of the prosurvival function of SIRT6 to suppress AMPK phosphorylation and promote COX2 expression." (PMID 32789493, 2020). "As a member of the sirtuin family, SIRT6 has received much attention due to its functions in DNA repair, genomic stability and restriction of tumor formation and the NF-κB signaling." (PMID 33042992, 2020). "Mainly in view of its role in DNA repair and in telomere biology and as a tumor suppressor in different cancer type, activation of SIRT6 is postulated to have beneficial effects and to promote healthspan." (PMID 32736564, 2020).
tumor (continued). "Regarding SIRT6, it is involved in regulating the energy metabolism of tumors as a tumor suppressor." (PMID 33335996, 2020). "We further evaluated the expression of SIRT6 on in vivo tumor growth in mice treated with doxorubicin." (PMID 33198792, 2020). "The NAD+-dependent deacetylase and mono-ADP-ribosyl transferase SIRT6 stabilizes the genome by promoting DNA double strand break repair, thereby acting as a tumor suppressor." (PMID 32789493, 2020). "While Sirt6 adopted a tumor suppressor role in pancreatic, breast and colon cancers, and hepatocellular carcinoma, a tumor promoter role was played by this protein in other cancer types such as lung, prostate, and melanoma." (PMID 32698385, 2020). "Derivatives of Quinazolinedione were recently discovered to inhibit Sirt6 activity, and these compounds were seen to sensitise the tumour cells to chemotherapeutic agents." (PMID 33442387, 2020). "Lower Sirt6 expression levels were confirmed in the xenograft tumor tissues derived from shSirt6 cells by IHC staining." (PMID 32711549, 2020). "As regards nuclear sirtuins, both Sirt6 and Sirt 7 are considered well-established tumor suppressors and when they are upregulated, they induce apoptosis and cell cycle arrest through HIF1/2 modulation." (PMID 32727075, 2020). "Western blotting confirmed the reduced Sirt6 expression in the xenograft tumor sections derived from shSirt6 cells." (PMID 32711549, 2020). "Xenograft models subjected to either OSS_128167 treatment or Sirt6-knockdown showed suppressed tumor growth and lower Ki-67 level." (PMID 32711549, 2020). "In orthotopic mouse model, NQO1 knock-out inhibited tumor growth and induced apoptosis while this effect was effectively rescued by SIRT6 overexpression or MG132 treatment partially." (PMID 31842909, 2019). "This double role in genomic stability and in metabolism can be translated into considering that SIRT6 has a tumor regulation activity." (PMID 31591350, 2019). "A previous study showed that miR-33 family members can suppress migration, invasion, and proliferation and promote apoptosis of tumor cells by regulating the expression of their target gene, abstract sirtuin 6 (SIRT6)." (PMID 31249647, 2019). "It was reported that SIRT6 has characteristics to be both a tumor suppressor and a carcinogenic factor." (PMID 31128573, 2019). "It was on account of SIRT6 exerted anti-tumor sphere-forming at the transcriptional level which was independent of SIRT6 histone deacetylase activity." (PMID 31842909, 2019). "Taken together, our results strongly suggested an important role of NQO1-induced SIRT6 stability in tumor biology of HCC." (PMID 31842909, 2019). "Evidence shows that SIRT6 overexpression or knockout in cells can result in different biological responses as tumor suppressor or promoter, depending on cell and tumor type." (PMID 31591350, 2019). "SIRT6 tumor suppressor activity is documented in pancreatic cancer, breast cancer, colon cancer, and HCCs." (PMID 30761005, 2019). "Altogether, the results demonstrated that UBCS039 is a specific activator of SIRT6 in several human tumor models." (PMID 30250025, 2018). "SIRT6 is involved in tumor progression by promoting cell cycle progression and tumor growth, inhibiting apoptosis, and enhancing EMT-related invasiveness of cancer cells." (PMID 30524965, 2018). "SIRT6 is predicted to act as a tumor suppressor principally because of its longevity potential and its regulation of genomic integrity." (PMID 29556059, 2018).
tumor (continued). "The expression of Cy-SIRT6 was significantly associated with serum level of CA125, tumor stage, bilaterality of the tumor, histologic grade, platinum resistance, and the expressions of Nu-Aβ-catenin, and Cy-Aβ-catenin." (PMID 30524965, 2018). "Unfortunately, at this stage, it is difficult to make definitive conclusions about the extent of insolvent of SIRT6 on cancer progression and tumor growth." (PMID 29966233, 2018). "A potential tumor suppressor function of SIRT6 in MM has also been shown, as knockdown of SIRT6 stimulates MM cell growth by activating MAPK pathway." (PMID 30190472, 2018). "The factors significantly associated with both OS or RFS in multivariate analysis were age of patients, tumor stage, bilaterality of the tumor, histologic grade, Nu-SIRT6 expression, and Nu-Aβ-catenin expression." (PMID 30524965, 2018). "In the year of 2012, SIRT6 was identified as a novel tumor suppressor by regulating aerobic glycolysis in cancer cells." (PMID 29100306, 2017). "SIRT6, a sirtuin with established tumor suppressor function, regulates the lysine fatty acylation of R-Ras2." (PMID 28406396, 2017). "Our data showed that overexpression of SIRT6 reduced the colony formation of HCC cells in soft agar and tumor growth in nude mice, which supported the opinion of SIRT6 as a tumor suppressor in HCC to a certain extent." (PMID 29100306, 2017). "On the contrary, SIRT6 suppression was observed in several types of cancer cells and therefore the proliferation of the tumor cells is accelerated." (PMID 27659520, 2017). "Additional studies have shown that the proliferation of embryonic fibroblasts (MEFs) was increased significantly and the Sirt6 knockout mice formed tumor tissue more easily." (PMID 28355287, 2017). "There is thus evidence to support conflicting functions for SIRT6 in cancer, either as a tumor suppressor and as a cancer-promoting factor under different circumstances." (PMID 27777384, 2016). "Taken together, our findings suggest that SIRT6 acts as a tumor promoter by preventing DNA damage and cellular senescence, indicating that SIRT6 represents a potential therapeutic target for the treatment of HCC." (PMID 27824900, 2016). "Significant differences in tumor volumes were observed at 22 days post-injection between SIRT6-depleted HCC cells and control HCC cells (P<0.05)." (PMID 27824900, 2016). "SIRT6 mRNA levels were significantly elevated in tumor tissues compared with those in non-tumor tissues (0.0167 versus 0.039; mean 2−ΔCT values, P< 2.2E−16)." (PMID 27824900, 2016). "SIRT6 plays a significant role in DNA repair and genomic stability and has been demonstrated to act as a tumour suppressor in liver and colorectal cancers." (PMID 26508273, 2016). "All these findings solidify the concept of SIRT6 being a key tumor suppressor, and further strengthen its role in delaying aging, since cancer incidence and progressive aging go hand in hand." (PMID 25907989, 2015). "Based on the reported tumor suppressor role of SIRT6, the decreased SIRT6 expression after treatment with HDAC inhibitor, TSA, reflects the complexity of developing HDAC inhibitor for cancer treatments." (PMID 25816777, 2015). "These published data based on in vivo models and primary tumor samples support our in vitro finding that E2F1 down regulates SIRT6 transcription and facilitates aerobic glycolysis." (PMID 25816777, 2015). "SIRT6 can be regarded as an important anti-aging protein with multifaceted roles in DNA damage repair, metabolic regulation, inflammation and also tumor suppression in details." (PMID 25907989, 2015).
tumor (continued). "It has already been demonstrated for SIRT1-3 and SIRT6 that they have the potential to function as both tumour suppressor and promoter not only within different tumour types, but also within tumours of the same tissue origin." (PMID 26121130, 2015). "While the SIRT2 and SIRT6 actually appear to be tumor suppressors, the most frequently studied subform SIRT1 seems to conditionally operate either as a tumor suppressor or as cancer promoting factor." (PMID 25310649, 2014). "This implicates SIRT6 as a tumor suppressor through its ability to down-regulate aerobic glycolysis in tumor cells." (PMID 25127496, 2014). "The finding that SIRT6 functions in regulating metabolism, genomic stability and cellular senescence – all phenomena relevant for neoplasia – has prompted multiple groups to assess roles for SIRT6 in cancer." (PMID 25085992, 2014). "In this Review, we highlight the importance of HIF1 and MYC in regulating tumor metabolism and their regulation by sirtuins, with a main focus on SIRT6." (PMID 25085992, 2014). "Collectively, these studies have shown that SIRT6 plays both oncogenic and tumor suppressor roles, in a cell- and context-specific manner." (PMID 25085992, 2014). "Some sirtuins, such as SIRT2 and SIRT6, seem to function as tumor suppressors, but others, such as SIRT1, are apparently bifunctional, operating as both tumor suppressors and oncogenic factors, depending on cellular context and study conditions." (PMID 25486244, 2014). "For example, SIRT6 acts as a nutrient sensor by linking epigenetic gene silencing and cellular energetics in maintaining genome stability and tumor suppression." (PMID 25127496, 2014). "Although we have focused on functions of SIRT6 in regulating MYC and HIF, it is very likely that other roles of SIRT6 are also relevant for its tumor suppressor capacity." (PMID 25085992, 2014). "The chromatin regulatory factor SIRT6 plays pivotal roles in metabolism, tumor suppression, and aging biology." (PMID 24169447, 2013). "The role of this enzyme in regulating energy homeostasis and tumor suppression will be discussed later in this review, as well as sirtuin 6 (Sirt6)." (PMID 24958265, 2013). "This study explored how Sirt6 affects tumor growth and immune surveillance." (PMID 41530841, 2026). "Additionally, we used transcriptomic analysis to explore the regulatory pathways of Sirt6 in tumor tissues." (PMID 41530841, 2026). "In addition, reduced SIRT6 expression seems to be correlated with the tumor initiation of liver and head and neck cancers." (PMID 39955062, 2025). "Furthermore, silencing of VDAC1 alters SIRT6-related epigenetic and metabolic networks to rewire tumor metabolism." (PMID 41463311, 2025). "SIRT6 has been a well-defined tumor suppressor in multiple cancers." (PMID 38954215, 2025). "Several studies have indicated that SIRT6 may play a tumor-suppressive role, attenuating and perhaps even antagonizing tumor development." (PMID 39955062, 2025). "Loss of SIRT6 in mouse embryonic fibroblasts (MEFs) led to tumor formation independent of oncogene activation, and the tumors exhibited enhanced aerobic glycolysis." (PMID 39955062, 2025). "Taken together, these findings indicate that BLA may inhibit tumor development by targeting SIRT6 to deacetylate histones H3K9Ac and H3K56Ac." (PMID 39845013, 2025). "Moreover, tumor-derived extracellular vesicles delivering miR-25 inhibit SIRT6, thereby promoting metastasis via the Lin28b/NRP-1 axis." (PMID 41463311, 2025). "The authors hypothesized that SIRT6 activation may be an additional HMAs attempt to repair the DNA of leukemic cells and restore tumor-suppressing genes." (PMID 40149343, 2025). "For example, in cases of malignancy, SIRT6 serves as both a tumor suppressor and an oncoprotein." (PMID 40806744, 2025). "Conversely, SIRT6 also exhibits tumor-suppressive properties in certain contexts." (PMID 41463311, 2025). "Recent studies demonstrates that SIRT6 is an important tumor suppressor in this context." (PMID 41463311, 2025).